IL2 (interleukin 2)
Diseases named in the same sentence as IL2 in open-access papers (continued):
Sharing a sentence is not in itself a finding about the gene and the disease.
COVID-19 (continued). "Conversely, significantly higher levels of GM-CSF, IFN-β, IL-10, and IL-2 and low levels of Eotaxin, IL-4, IL-5, MCP-1, and MIP-1β, were distinctive to Non-SOT COVID-19 patients relative to HCs, but not in SOTRs." (PMID 35075453, 2022). "The canonical transcript usage of IL2 was significantly decreased and the ENST00000477645 (noncoding protein) transcript usage was significantly increased in COVID-19 cases." (PMID 35421082, 2022). "In this study, IL-1 β, IL-2, LTB-4, CCL-2, and IL-8 levels were higher in all COVID-19 patients (survivors and non-survivors) compared with the levels in the healthy control group." (PMID 36294868, 2022). "Compared to non-hospitalized COVID-19 patients, severe cases showed increased cytotoxic Tfh cells which manifested high levels of IFN-γ, IL-2, and TNF-α." (PMID 36505489, 2022). "While the levels of IP-10, IL-15 and IL-18 were exclusively increased in SOTRs with COVID-19, Non-SOT patients with COVID-19 showed solely higher levels of IFN-β, IL-2, IL-10, GM-CSF and low levels of Eotaxin, MCP-1, MIP-1β, IL-4, IL-5." (PMID 35075453, 2022). "We also noted that, in the COVID-19-naive population, the frequency of AIM+IL-2+CD8+ T cells (but not IFNγ+ or TNFα+CD8+ T cells) was greater among the older subjects compared with the young group." (PMID 34868051, 2021). "Healthy pregnant women showed high levels of interleukins including IL-2, IL-5, IL-10, and IL-12, as well as high levels of growth factors such as b-NGF and VEGF, which were largely decreased in COVID-19 pregnant and non-pregnant patients." (PMID 34012458, 2021). "In our study, in both of the COVID-19 groups of patients IL-2 was at the lowest level, TNFα was only slightly elevated, while INFγ was significantly higher in the non-ICU COVID-19 patients." (PMID 34071149, 2021). "Proinflammatory molecules, such as IL-2, IL-4, IL-5, IL-6, IL-10, IL-13, TNF-α, IFN-Υ, and CRP, were found at higher levels in COVID-19 patients with DM than in COVID-19 patients without DM." (PMID 34786431, 2021). "Compared with that in the non-COVID-19 group, the levels of Interleukin-2 (IL-2), Interleukin-6 (IL-6), Interferon-gamma (IFN-γ) and tumor necrosis factor-alpha (TNF-α) were significantly increased in the COVID-19 group (P < 0.05)." (PMID 35071136, 2021). "The IL-2 levels in both the non-ICU and ICU COVID-19 patients were low (median level 0.29 pg/mL), almost within the normal ranges, whereas the levels of TNFα were slightly elevated in both the studied groups." (PMID 34071149, 2021). "In the nonsevere COVID-19 group, the correlation coefficients of IL-4 and IL-2, TNF-α and IL-2, TNF-α and IFN-γ, and TNF-α and IL-4 were 0.887, 0.795, 0.699, and 0.674, respectively." (PMID 34712741, 2021). "Interleukin-2, overexpressed in both ICU-COVID-19 and non-ICU COVID-19 patients, indicating a Th1 immune reaction to SARS-CoV-2, is a T-cell growth factor of key importance in immune-reactive processes." (PMID 33182653, 2020). "These events collectively inhibit IL-2/STAT5-dependent Foxp3 sustenance while inducing negative regulators such as RORγt and T-bet, as evidenced by the overrepresentation of Tbet+ Tregs in severe COVID-19 patients." (PMID 40806563, 2025). "Similarly, the plasma level of IL-2, IL-7, IL-10, and TNF-α increased in ICU COVID-19 patients compared to non-ICU COVID-19 patients." (PMID 38152668, 2023). "We found that the patients who had severe COVID-19 had low or absent cellular immune responses of CD4+IL-2+, CD4+IFN-γ+IL-2+, CD8+IFN-γ+IL-2+, and CD8+IFN-γ+IL-2+TNF-α+ after a booster dose, in line with the relevance of polyfunctional T cell responses against viruses." (PMID 37243116, 2023). "One of the first studies to evaluate the serum cytokine storm in COVID-19 patients showed that several pro-inflammatory mediator levels, such as TNFα, IL-2, IL-7, IL-10, G-CSF, CXCL10, CCL2 and CCL3, were increased in ICU (n = 13) compared to non-ICU COVID-19 patients (n = 28)." (PMID 36941580, 2023).
COVID-19 (continued). "Furthermore, IL-2, IL-7, IL-10, G-CSF, IP-10, MIP-1α and1β, and TNF-α were higher in ICU COVID-19 patients than non-ICU patients." (PMID 35401519, 2022). "Both studies uniformly describe stable cellular immune responses against SARS-CoV-2 including IFN-γ release as does our study but also of other cytokines (IL-2, IL-4, TNF-α etc.)and proliferation assays in SOT convalescents similar to non-IS-Con up to twelve months after COVID-19." (PMID 36322587, 2022). "Number of IFN-γ, IL-2, and both IFN-γ and IL-2 producing cells, measured by ELISpot after stimulation of PBMC in vitro with a SARS-CoV-2-specific peptide library (SI values) in men and women with and without post-COVID-19 fatigue." (PMID 35693828, 2022). "We have found that, in patients in whom there was a clinical deterioration following SARS-CoV-2 infection, the initial inflammatory response in the airway is blunted with reduced concentrations of IL-2, IL-33, IL-12, and IFN-α2a, in comparison with patients with COVID-19 without deterioration." (PMID 35397798, 2022). "After stimulation with controls and peptide pools spanning SARS-CoV-2 wt and Delta spike proteins, interferon gamma (IFN-γ) and interleukin 2 (IL-2) mRNA levels in total cellular RNAs were measured with RT-qPCR from PBMC samples of 15 vaccinees, 10 COVID-19 patients, and 10 negative controls." (PMID 35529867, 2022). "Compared to nondiabetic COVID-19 patients, diabetic COVID-19 patients are characterized by a higher percentage of CD4+ T cell and a lower percentage of CD8+ T cells and higher serum levels of IL-6, IL-2, IL-10, and INFγ." (PMID 34157054, 2021). "Moreover, the correlation coefficients for IL-4 and IL-2, IL-4 and TNF-α, and NK cells and T cells were the lowest in nonmetastatic patients, followed by metastatic and nonsevere COVID-19 patients, and were the highest in severe COVID-19 patients." (PMID 34712741, 2021). "Serum inflammatory factor levels of IL-2, IL-1β, IL-5, IL-4, IL-6, IL-8, IL-10, IL-17, IL-12P70, IFN-α, TNF-α, IFN-γ, endotoxin, CRP, and hs-CRP of non-severe COVID-19 patients across different age groups (< 50, 50–60, 60–70, and ≥ 70 years) were not significantly different." (PMID 33065551, 2020). "Similarly, in severe COVID-19 cases, ICU patients had higher plasma levels of IL-2, IL-7, IL-10, GSCF, MCP1, MIP1A, and TNFα compared to non-ICU patients." (PMID 32754890, 2020). "We found that virtually all genes upregulated in IL2-AIS had negative loading scores in Component 187 and vice versa, indicating a strong inverse correlation between the differential gene expression induced by IL-2 treatment in T1D patients and the response to infection in COVID-19 patients." (PMID 37700317, 2023). "Furthermore, we found low levels of IL-2 and APRIL/TNFSF13 (two immune mediators crucial for T-cell and plasma cell survival), as well as sCD30 (a marker of lymphocyte activation) in the circulation of COVID-19 but not pandemic influenza A(H1N1) patients." (PMID 33995342, 2021). "However, another study which included 25 confirmed COVID-19 patients who were admitted to ICU showed that circulating levels of IL-2, interleukin-4 (IL-4), tumor necrosis factor-α (TNF-α), interferon (IFN-γ) and CRP were not directly correlated with symptom severity of COVID-19." (PMID 34282057, 2021).
metastatic melanoma (384 papers, 1990 to 2026). A melanoma that has spread from its primary site to another anatomic site. "Different mutation status in patients with metastatic melanoma treated with high‐dose IL‐2 had a statistically significant difference in the response rate (CR or PR) in a multicenter retrospective study." (PMID 41492362, 2026). "The role of IL-2 in expanding tumor-infiltrating lymphocytes and supporting durable responses is well documented, with high-dose IL-2 therapy historically approved for metastatic melanoma and associated with improved outcomes in selected patients." (PMID 41020868, 2025). "Twenty patients with metastatic melanoma were treated with intravenous infusion of TILs, followed by injecting IL-2, which caused objective responses of eleven patients." (PMID 38693513, 2024). "In particular, the use of interferon alpha (IFN-α) and interleukin 2 (IL-2) associated with cytotoxic drugs has been evaluated for the treatment of metastatic melanoma." (PMID 36286442, 2022). "Since IL-2 based immunotherapy is efficient against metastatic melanomas, albeit associated with toxicity, we designed a tumor-targeting FAP-IL2v with abolished CD25 binding." (PMID 35874707, 2022). "High dose interleukin-2 (IL-2) is active against metastatic melanoma and renal cell carcinoma, but treatment-associated toxicity and expansion of suppressive regulatory T cells (Tregs) limit its use in patients with cancer." (PMID 32005826, 2020). "Treatment with IL-2 has been associated with stable and curative regressions in patients with metastatic melanoma, renal cancer and advanced non-Hodgkin's lymphomas, representing the first effective immunotherapeutic agent." (PMID 30619269, 2018). "We sequenced vemurafenib with HD IL-2 in patients with BRAF-mutated metastatic melanoma to improve long term outcomes." (PMID 30053905, 2018). "ALT-801 is an innovative immunotherapeutic fusion protein consisting of interleukin-2 (IL-2), an approved cytokine for treatment of metastatic melanoma and renal cell carcinoma, linked to a single-chain T-cell receptor domain." (PMID 28134806, 2017). "HD IL-2 produces durable, complete remission for a small percentage of metastatic melanoma patients (<10%), but has been associated with severe toxicity and its efficacy against brain metastases is limited." (PMID 27598148, 2016). "IL-2 has been associated with objective response rates of 16-20% in patients with metastatic melanoma and responders have durable tumor control with nearly 90% of complete responders free of disease recurrence up to 15 years following treatment." (PMID 25992289, 2015). "High-dose IL-2 is associated with prolonged survival in selected individuals and is a potentially curative therapy in metastatic melanoma; hence, it deserves special consideration." (PMID 25932372, 2015). "In our study, development of autoimmune phenomena in metastatic melanoma was associated with response to IL-2." (PMID 25815245, 2015). "We aimed to identify clinical characteristics and biomarkers associated with response to high-dose interleukin-2 therapy (IL-2) in patients with metastatic melanoma and renal cell carcinoma treated at an academic community hospital." (PMID 25815245, 2015). "Treatment with high-dose interleukin-2 (IL-2) has induced a durable complete remission in a minority of patients with metastatic melanoma, but this treatment is associated with severe toxicity and it is not widely available." (PMID 20180962, 2010). "C-reactive protein was introduced in this study as elevated levels in serum have been associated with shortened survival in metastatic melanoma patients and resistance to interleukin-2 therapy." (PMID 15280926, 2004). "Twenty-eight patients with metastatic melanoma were included: R24 was associated with a high toxicity rate, including cytokine-released syndrome or anaphylaxis, related to the murine origin of the antibody and the well-known toxicity of IL-2." (PMID 38590763, 2024).
metastatic melanoma (continued). "In addition, high-dose IL-2, although linked to higher response rates in metastatic melanoma, is associated with increased toxicity." (PMID 37516849, 2023). "Recombinant human IL-2 (Proleukin, aldesleukin) was approved by the United States Food and Drug Administration for metastatic melanoma and renal cell cancer; however, adverse events associated with high-dose IL-2, including capillary leak syndrome (VLS), limit its therapeutic use." (PMID 36230665, 2022). "IL-2 may be a cause of itch, as systemic treatment of metastatic melanoma with IL-2 induces severe itch." (PMID 28698528, 2017). "Among the CXCL chemokines, CXCL-12/SDF-1 was previously associated with the rejection of metastatic melanoma during IL-2 therapy and together with CXCL-9 through -11 chemokines in association with the rejection of basal cell carcinomas (BCCs) treated with TLR7 agonists." (PMID 19583830, 2009). "Finally, in a phase Ib study of patients with metastatic melanoma, the association between pembrolizumab (200 mg IV every 3 weeks) and escalating doses of IL-2 (6000 or 60,000 or 600,000 IU/kg IV bolus every 8 h up to 14 doses per cycle) was evaluated in cohorts of three patients." (PMID 37569757, 2023). "A high-dose IL2 regimen administered every 8 hours in a hospital setting using an IL2 variant known as ‘aldesleukin’ was approved in the 1990s by the United States Food and Drug Administration for the treatment of metastatic melanoma and renal cell carcinoma, providing up to 25% durable responses." (PMID 28678791, 2017). "In summary, factors significantly associated with response to IL-2 from our single institutional experience in treating patients with MM or mRCC include development of autoimmune phenomena including secondary hypothyroidism, vitiligo and neuropathy in metastatic melanoma and lower platelet nadir." (PMID 25815245, 2015). "In a retrospective analysis, high‐dose IL‐2 therapy showed durable antitumor activity in metastatic melanoma patients (n = 40) who previously received PD‐1 or PD‐L1 inhibitors." (PMID 41492362, 2026). "High‐dose interleukin‐2 (IL‐2) has been approved as an immunotherapy regimen for metastatic melanoma since 1998." (PMID 41492362, 2026). "Despite the availability of numerous approved regimens for metastatic melanoma, high‐dose IL‐2 remains an important treatment option." (PMID 41492362, 2026). "High‐dose IL‐2 sequenced with vemurafenib was investigated for BRAFmut metastatic melanoma in a multicenter Phase II study (NCT01683188)." (PMID 41492362, 2026). "High‐dose IL‐2 represents a treatment option in patients with metastatic melanoma after first‐line ICIs‐based immunotherapy and BRAF/MEK‐targeted therapy." (PMID 41492362, 2026). "In the 1990s, high-dose IL2 was approved to treat metastatic renal cell carcinoma and metastatic melanoma but has had limited clinical impact due to significant toxicities." (PMID 39301613, 2025). "Interleukin-2 (IL-2) and interferon-alpha were among the first immunotherapeutic agents approved for treating metastatic melanoma, marking an early phase in the evolution of immunotherapy for this cancer." (PMID 40746887, 2025). "High-dose IL-2 (HD IL-2) has received regulatory approval for the treatment of metastatic melanoma and metastatic renal cell carcinoma, demonstrating an overall response rate of 10-25% in these patient populations." (PMID 40046051, 2025). "IL-2 treatment has shown significant efficacy in metastatic melanoma, RCC, and advanced non-Hodgkin’s lymphoma." (PMID 39852848, 2025). "TILs have shown efficacy in eradicating metastatic melanoma, even more than some previous therapeutic regimens such as various ipilimumab therapy plans or systemic IL-2 treatment in some cases." (PMID 40564107, 2025).
metastatic melanoma (continued). "While high-dose IL-2 has demonstrated durable efficacy in a subset of patients with metastatic melanoma and RCC, its severe toxicities, such as vascular leak syndrome and cytokine release syndrome, have limited its broader clinical application." (PMID 39852848, 2025). "This study explored the combination of fibroblast activation protein (FAP) IL2 variant (FAP-IL2v), a novel immune-cytokine, with pembrolizumab in patients with advanced and/or metastatic melanoma." (PMID 39895413, 2025). "Interleukin-2 (IL-2)-based therapies have shown efficacy in cancers such as metastatic melanoma and renal cell carcinoma but are limited by severe side effects." (PMID 39852848, 2025). "In a Danish pilot trial of six patients with metastatic melanoma treated with TILs, low-dose IL-2 (200,000 IU/kg for 14 days) considerably decreased the treatment-related toxicity, with no grade 3 to 4 IL-2-related AEs reported." (PMID 40458394, 2025). "Secondly, IL-2 is itself an approved drug against metastatic melanoma with limited effect and toxicity, but oncolytic viruses promise improved delivery." (PMID 40954493, 2025). "For example, in a phase II study in metastatic melanoma evaluating TILs together with low-dose subcutaneous IL-2, a proportion of patients achieved partial responses, while others experienced disease stabilization, indicating clinically relevant activity." (PMID 41438682, 2025). "18F-labeled-IL2 has been used in a small cohort of metastatic melanoma patients to monitor the response to immune checkpoint inhibitor therapy." (PMID 40869484, 2025). "The potential danger of systemic toxicity is seen in such cytokine-based therapy as high dose interleukin-2 (IL-2) given to metastatic melanoma or renal cell carcinoma." (PMID 41465368, 2025). "In the 1990s, the FDA approved interleukin-2 (IL-2) for the treatment of renal cell carcinoma and metastatic melanoma." (PMID 40028340, 2025). "According the historical data, the response rate after using high doses of the wild type IL-2 was 15% in renal cell carcinoma patients and 16% in metastatic melanoma." (PMID 40486521, 2025). "IL-2 has been approved for the treatment of metastatic renal cell carcinoma and metastatic melanoma." (PMID 38256080, 2024). "Thirty-one metastatic melanoma patients who depleted their lymphocytes by using cyclophosphamide and fludarabine in advance, were treated with their harvested TILs and high-dose IL-2." (PMID 38693513, 2024). "In the treatment of metastatic renal cell carcinoma and metastatic melanoma, IL‐2 has been approved by the FDA as a monotherapy." (PMID 38647237, 2024). "The FDA approved high-dose IL-2 therapy for metastatic renal cell carcinoma and metastatic melanoma; however, other tumor types showed limited responses." (PMID 38672545, 2024). "High-dose IL-2 therapy has been fundamental in the treatment of metastatic melanoma and renal cell carcinoma, primarily due to its capacity to enhance the expansion and activation of cytotoxic T cells and NK cells." (PMID 39483536, 2024). "For example, IL-2, a cytokine initially discovered in human peripheral blood leukocytes, demonstrated significant anti-tumor potential in the 1980s, notably in metastatic melanoma and renal cancer." (PMID 38672545, 2024). "Studies in humans yielded positive results as well: the use of TIL in patients with metastatic melanoma showed a response rate of 35% in patients receiving TIL along with IL-2 and cyclophosphamide." (PMID 39682188, 2024). "Twenty patients with metastatic melanoma in that research trial were given an infusion of a cultured solution containing TILs and IL-2." (PMID 39712007, 2024). "This approach leads to 56% objective responses in treatment-naïve patients with metastatic melanoma, thus highlighting the important role of IL-2 in this promising therapy." (PMID 38928238, 2024).